CHIT1 (chitinase 1)
Diseases named in the same sentence as CHIT1 in open-access papers (continued):
Sharing a sentence is not in itself a finding about the gene and the disease.
sarcoidosis (13 papers, 2016 to 2025). Sarcoidosis is a multisystemic disorder of unknown cause characterized by the formation of immune granulomas in involved organs. "The potential role of CHIT1 during the diagnostic process of active sarcoidosis patients was further reinforced by recent reports correlating the enzyme’s levels with disease activity, severity, and multi-organ dissemination." (PMID 34830565, 2021). "It was recently shown that active sarcoidosis could be differentiated from the inactive one through an algorithm involving the association of plasma CHIT1 activity, ACE levels, and high-sensitivity C-reactive protein (hs-CRP) levels." (PMID 34830565, 2021). "On the other hand, CHIT1 appeared as an interesting potential biomarker of sarcoidosis activity/severity during the diagnostic process, as high CHIT1 values are indicative of the disease in its active phase, whereas the enzyme activity lowers under treatment or in the remission state of the disease." (PMID 34830565, 2021). "In contrast, both Mac 1 and Mac 2 in sarcoid granulomas adopted an inflammatory state with sarcoidosis-specific gene activation, including CHIT1, PTGDS, and PLA2G7." (PMID 39225100, 2024). "CHIT1 is a well-known biomarker in lung sarcoidosis, which correlated with diseases severity and progression." (PMID 38550597, 2024). "There are many lines of evidence reporting that CHIT1 is elevated in sarcoidosis patients compared to healthy controls and that the enzyme levels correlate with the severity of the disease and with the response to corticosteroid therapy." (PMID 34830565, 2021). "In the active sarcoidosis group, when compared to FUO patients, CHIT1 values showed a significant accuracy in discriminating active sarcoidosis from other diseases (AUROC: 0.955, CI 95%: 0.895–0.986, p < 0.001)." (PMID 34830565, 2021). "CHIT1 showed a good accuracy as a biomarker for active sarcoidosis in patients explored for FUO (AUROC 0.955; CI 95% 0.895–0.986; p < 0.001)." (PMID 34830565, 2021). "Sarcoidosis patients have higher CHIT1 serum concentrations than healthy individuals; its activity in bronchoalveolar lavage (BAL) and serum is also significantly increased, especially in the advanced stages of the disease." (PMID 34203467, 2021). "In conclusion, CHIT1 is a reliable/sensitive biomarker of active sarcoidosis, with values significantly decreasing in remitted/treated patients." (PMID 34830565, 2021). "On the other hand, the ROC analysis confirmed that CHIT1 distinguishes between before and after therapy sarcoidosis patients." (PMID 34830565, 2021). "CHIT1 is receiving attention as a potential biomarker of sarcoidosis compared to ACE." (PMID 34830565, 2021). "The active sarcoidosis group (before therapy) was compared to patients in remission/under treatment (indicated as “after therapy”) to address whether CHIT1 versus ACE could discriminate between the different phases of the disease." (PMID 34830565, 2021). "We also showed that CHIT1 significantly discriminated between active and under remission sarcoidosis disease as already reported, with a sensitivity and specificity of 96.9% (84.2–99.9) and 94.7% (74.099.9), respectively, and AUROC = 0.958 (0.862–0.994) (p < 0.001)." (PMID 34830565, 2021). "Although, it has been demonstrated that serial measurements of serum CHIT1 correlate with clinical symptoms, chest radiographs, and lung function in sarcoidosis and may have the potential as high specificity biomarker of extrapulmonary manifestations of the disease." (PMID 35222369, 2022). "Furthermore, we addressed the question whether the value of CHIT1 could discriminate a patient with sarcoidosis in active phase from a patient with sarcoidosis in a remission/inactive state." (PMID 34830565, 2021). "In the present study, a CHIT1 value >90.86 nmol/mL/h differentiated between active sarcoidosis and FUO patients not affected by sarcoidosis with high sensitivity and specificity [96.8% (84.2–99.9) and 85.5% (75.0–92.8), respectively]." (PMID 34830565, 2021).
amyotrophic lateral sclerosis (12 papers, 2017 to 2025). Amyotrophic lateral sclerosis (ALS) is a neurodegenerative disease characterized by progressive muscular paralysis reflecting degeneration of motor neurons in the primary motor cortex, corticospinal tracts, brainstem and spinal cord. "CHIT1 is also elevated in patients with type 2 diabetes, amyotrophic lateral sclerosis (ALS), and childhood asthma, and it is generally accepted that CHIT1 reflects macrophage or microglial activation in these conditions." (PMID 40098951, 2025). "CHIT1 concentrations were elevated in treatment-naïve SMA patients as compared to controls, but less pronounced than described for other neurodegenerative diseases such as amyotrophic lateral sclerosis." (PMID 34321067, 2021).
atherosclerosis (12 papers, 2013 to 2025). A disease characterized by the build-up of fatty material and calcium deposition in the arterial wall resulting in partial or complete occlusion of the arterial lumen. "To extend our understanding of the inflammatory mechanisms affected by CHIT1 overexpression, we investigated inflammatory signaling pathways associated with atherosclerosis." (PMID 32655419, 2020). "Our findings demonstrate that CHIT1 overexpression in vitro augmented the transcription and expression of cytokines and chemokines associated with atherosclerosis." (PMID 32655419, 2020). "Given the importance of macrophages in every stage of atherosclerosis and the fact that CHIT1 is among the most abundantly expressed proteins by activated macrophages, we wished to investigate the presence of CHIT1 in the plaques of our control mice." (PMID 32655419, 2020). "Previously published data from our group showed that CHIT1 inhibition using a chitinase inhibitor, allosamidin, promotes atherosclerosis in ApoE–/– mice." (PMID 32655419, 2020). "Our research further demonstrated that inhibition of CHIT1 with allosamidin promoted atherosclerosis in hyperlipidemic mice." (PMID 32655419, 2020). "Results generated from this work demonstrate that, in vitro, CHIT1 modulates macrophage transcription and protein expression of chemokines and cytokines that are central to inflammation and atherosclerosis." (PMID 32655419, 2020). "Proteins related to atherosclerosis/cardiovascular risk (e.g., SELE/E-selectin, IGFBP7, CHIT1/ chitotriosidase-1, AXL) also significantly decreased after treatment." (PMID 32849633, 2020). "Notably, it was demonstrated that CHIT1 can have a protective effect during the development of experimental atherosclerosis, whereas some authors reported increased serum CHIT1 activity in patients with atherosclerosis." (PMID 35330193, 2022). "CHIT1/chitotriosidase-1, secreted by activated macrophages, is expressed at higher levels in patients with atherosclerosis in a severity-dependent manner, and may be a predictor of endothelial dysfunction and insulin resistance in type 2 diabetes." (PMID 32849633, 2020). "Because we observed an exacerbation of atherosclerosis by inhibiting CHIT1, we sought to examine if overexpression of CHIT1 in macrophages may exhibit possible athero-protective properties." (PMID 32655419, 2020). "The data presented here suggest a novel, nonenzymatic role for CHIT1 in inflammation and atherosclerosis." (PMID 32655419, 2020). "Chitinase 1 (CHIT1), secreted by activated macrophages, could curb inflammatory responses, promote lipid uptake and cholesterol efflux in macrophages, and polarize macrophages towards an M2 phenotype, thus exerting protective effects against atherosclerosis." (PMID 30923552, 2019).
chronic obstructive pulmonary disease (11 papers, 2012 to 2024). A chronic and progressive lung disorder characterized by the loss of elasticity of the bronchial tree and the air sacs, destruction of the air sacs wall, thickening of the bronchial wall, and mucous accumulation in the bronchial tree. "CHIT1 is a hydrolase produced by activated alveolar macrophages and has been investigated as a serum biomarker in several lung diseases, including chronic obstructive pulmonary disease." (PMID 34954872, 2022). "For instance, the levels of Chit1 are elevated in the plasma of patients with Gaucher disease, the bronchoalveolar lavage fluid of smokers and patients with chronic obstructive pulmonary disease (COPD) and the cerebrospinal fluid of patients with Alzheimer’s disease." (PMID 23826286, 2013). "Chronic obstructive pulmonary disease and asthma are hallmarked by the dysregulation of inflammatory processes and airway chitinases (YKL-40 and CHIT1) represent biomarkers of COPD phenotyping." (PMID 38125621, 2024). "For instance, the levels of CHIT1 are elevated in Gaucher disease, smokers and chronic obstructive pulmonary disease (COPD), and in the cerebrospinal fluid of patients with Alzheimer’s disease." (PMID 29747453, 2018). "The levels of Chit1 are significantly upregulated in Gaucher disease, chronic obstructive pulmonary disease (COPD), Alzheimer’s disease, atherothrombosis, diabetes mellitus, cystic fibrosis as well as in smokers." (PMID 29362395, 2018).
asthma (8 papers, 2011 to 2025). "Their study suggests that CHIT1 is capable of altering glycosylation associated with diseases, including asthma." (PMID 38785919, 2024). "CHIT1 contributes to macrophage polarization, a process detrimentally linked to asthma, as well as a complex pathway driving airway remodeling." (PMID 38785919, 2024). "Despite the lack of endogenous chitin synthesis, mammalian genomes encode CHIT1, which is a biomarker of various diseases including asthma." (PMID 38785919, 2024). "Intranasal delivery of chitin induced an accumulation of immune cells which was mainly dependent on AMCase, while an increased asthma risk is suggested to be primarily the consequence of CHIT1 polymorphisms." (PMID 29892291, 2018). "Although we focused on the potential implications of CHIT1 inhibition in the context of asthma severity and airway remodeling, other enzymes hold therapeutic promise for glycosylation regulation, such as galectins, NEU1, and FUT2." (PMID 38785919, 2024). "Here, we discuss in detail all of the endogenous substrates for CHIT1, including glycans, in the context of asthma, which we believe far better reflect physiologically relevant substrates for CHIT1 in diseases." (PMID 38785919, 2024). "Taking into consideration the fact that CHIT1 activity was shown to be elevated along with CCL18 in the model for allergic airway inflammation in asthma, these findings shed a new light on the role of chitinolytic enzymes in lung disease." (PMID 38785919, 2024). "These recent findings demonstrate the therapeutic potential of targeting CHIT1 in all disorders with chronic inflammation, including asthma as a perfect example." (PMID 38785919, 2024). "CHIT1 is therefore a profibrotic macrophage functional biomarker contributing to fibrotic lesion progression leading to airway remodeling in severe asthma." (PMID 36902148, 2023). "The overall effect of CHIT1 inhibition resulted in less collagen deposition in extracellular space and attenuated airway remodeling observed in severe asthma." (PMID 36902148, 2023). "Due to macrophage-specific localization of CHIT1 in remodeled airways of fatal asthma patients, we chose a 7-week-long HDM administration when alveolar macrophage accumulation (CD11cpos and SiglecFpos) was significantly induced." (PMID 36902148, 2023). "CHIT1 is a dominant chitinase activated in fibrotic areas of the lungs of individuals with fatal asthma." (PMID 36902148, 2023). "As profibrotic and pro-homeostatic macrophage phenotypes remain ill-defined, CHIT1 can also be a useful functional marker for different asthma endotypes." (PMID 36902148, 2023). "Our conclusions and observations extend beyond severe asthma, presenting CHIT1 inhibition as a novel and attractive therapeutic target for other disorders regulated by profibrotic macrophages, specifically IPF and other ILDs." (PMID 36902148, 2023). "Comparison of lung specimens obtained from control donors (n = 9) and from individuals with fatal, steroid-naïve asthma (n = 12) revealed increased CHIT1-positive staining localized in the remodeled small airways." (PMID 36902148, 2023). "Here, we present reprograming of profibrotic, CHIT1-expressing macrophages as a successful therapeutic approach to manage airway remodeling in severe asthma." (PMID 36902148, 2023). "We demonstrate that activation of CHIT1 is observed in fatal asthma, but more importantly we present OATD-01 as a safe and efficacious drug." (PMID 36902148, 2023). "CHIT1 expression was evaluated in the lung tissues of deceased individuals with severe, uncontrolled, steroid-naïve asthma." (PMID 36902148, 2023). "This specific population provided valuable information about significant changes in CHIT1 expression in the lungs of unmedicated severe asthma patients." (PMID 36902148, 2023). "Further studies need to be performed to assess whether CHIT1 expression can help to stratify patients with different endotypes of asthma, as it was suggested for COPD patients." (PMID 36902148, 2023).
asthma (continued). "Therefore, we claim that CHIT1 is a valid therapeutic target in tissue remodeling processes and fibrosis occurring in severe asthma." (PMID 36902148, 2023). "Importantly, immunohistochemical localization studies for the first time revealed CHIT1 involvement in human fatal asthma, where CHIT1 was localized in the surroundings of severely remodeled airways and AMCase was not present." (PMID 36902148, 2023). "Lung macrophages have been implicated in asthma development; therefore, we asked whether pharmacological inhibition of macrophage-specific CHIT1 would have beneficial effects in asthma, as it has been shown previously in other lung disorders." (PMID 36902148, 2023). "It has also been shown that high mold exposure can significantly modulate the effect of SNPs in CHIT1 gene on severe asthma exacerbations leading to increased hospitalizations- an example of gene-environment interactions as a determinant for an outcome of the disease." (PMID 22410255, 2011). "Moreover, CHIT1 participates in macrophage polarization, a process which is detrimental to asthma." (PMID 36902148, 2023). "Therefore, we hypothesized that inhibition of CHIT1 can alter macrophage biology and have a positive outcome on asthma development." (PMID 36902148, 2023). "Chitinase-1 suppression by CPX can regulate PM10- and OVA-induced and aggravated airway inflammation and fibrosis via an asthma-related signaling pathway." (PMID 36934237, 2023). "We showed that chitinase-1 suppression by CPX can regulate PM10- and OVA-induced and aggravated airway inflammation and fibrosis via an asthma-related signaling pathway." (PMID 36934237, 2023). "The relevance of the pathological role of CHIT1 in asthma was demonstrated by pre-clinical models with genetically modified mice lacking CHIT1." (PMID 38785919, 2024).
fungal infection (8 papers, 2012 to 2025). "Aside from fungal infections, in a murine model of interstitial lung disease, a manifestation of systemic sclerosis, Chit1 deficiency prevented fibrotic lung damage, while transgenic Chit1 overexpression promoted it." (PMID 40098951, 2025). "In agreement with our data, patients with CHIT1 deficiency-associated polymorphisms have higher colonization levels by C. albicans and an increased risk of fungal infection by Madurella mycetomatis, the causative agent of mycetoma." (PMID 40098951, 2025). "If the Chit1 protein is inhibiting the inflammatory response, then increased susceptibility to fungal infections would be associated with disorders overexpressing Chit1." (PMID 33796101, 2021). "Therefore, a thorough immunogenetic haplotype analysis that involves CHIT-1 and AMCase alleles, as well as chitin sensing and chitinase regulation pathways is needed to investigate the significance of human chitinase responses to fungal infections." (PMID 22187561, 2012). "To determine the importance of Chit1 in the inflammatory response to fungal infection we used a mouse model of systemic candidiasis." (PMID 33796101, 2021). "Lastly, we observed increased Chit1 activity in humans with confirmed fungal infections, reinforcing the relevance of Chit1 in human disease." (PMID 25764512, 2015). "Additionally, the enzymatic activity of Chit1 on fungally-derived chitin can increase the concentration of chitobiose at the site of a fungal infection, specifically at the neutrophil:Candida interface." (PMID 33796101, 2021). "During the process of fungal infection of insect body surfaces, enzymes such as protease (Pr1A) and Pr1A like proteases CDEP1, and chitinase CHIT1, are synthesized to dissolve insect body walls and aid in fungal penetration." (PMID 37888243, 2023). "Nonetheless, it has not been determined whether CHIT-1 secretion increases during fungal infections." (PMID 24722226, 2014).
idiopathic pulmonary fibrosis (8 papers, 2020 to 2025). Idiopathic pulmonary fibrosis (IPF) is a nonneoplastic pulmonary disease that is characterized by the formation of scar tissue within the lungs in the absence of any known cause. "One of the most comprehensive resources for lung cell data is the Human Lung Cell Atlas, which has identified a population of SPP1+ macrophages co‐expressing LPL and CHIT1 across various disease conditions, including COVID‐19 and idiopathic pulmonary fibrosis (IPF)." (PMID 40395129, 2025).
multiple sclerosis (8 papers, 2017 to 2025). A progressive autoimmune disorder affecting the central nervous system resulting in demyelination. "The neurofilament light chain (NfL) protein, another biomarker for axonal loss, also correlates with CSF CHIT1 levels in patients with ALS and multiple sclerosis." (PMID 36052089, 2022). "For example, in multiple sclerosis, an increase in CHIT1 has been reported in the literature, which is in agreement with our findings." (PMID 34359293, 2021). "One control patient with multiple sclerosis displayed the highest level of CHIT1 (16,456 pg/mL), CHI3L1 (357 ng/mL) and CHI3L2 (36 ng/mL), but not pNFH (355 pg/mL)." (PMID 34359293, 2021). "Chitotriosidase-1 (CHIT1), a glycosyl hydrolase secreted predominantly by activated microglia, has emerged as a robust biomarker candidate for predicting neurodegeneration in multiple sclerosis (MS)." (PMID 40361996, 2025). "While CHIT-1 is shown to have a pro-inflammatory potential in neurological disorders like stroke, its neuroprotective role in the inflammatory conditions like multiple sclerosis has also been suggested." (PMID 29246232, 2017).